RNU6-243P (RNA, U6 small nuclear 243, pseudogene)
Gene: Small nuclear RNA gene on chromosome 3 (35,256,840 to 35,256,946, reverse strand). Ensembl gene ENSG00000212442.
Homologues: Orthologues: chimpanzee U6 (100% identical), macaque U6 (91% identical), dog U6 (70% identical). Paralogues in human: RNU6V (82% identical), RNU6-589P (81% identical), RNU6-968P (81% identical), RNU6-1060P (79% identical), RNU6-1181P (79% identical), RNU6-1201P (79% identical), RNU6-259P (79% identical), RNU6-26P (79% identical), RNU6-45P (79% identical), RNU6-873P (79% identical), RNU6-883P (79% identical), RNU6-1011P (79% identical), and 1286 more.